FAM110C (family with sequence similarity 110 member C)
Description:
May play a role in microtubule organization. May play a role in cell spreading and cell migration of epithelial cells; the function may involve the AKT1 signaling pathway.
Tractability: No criterion of Open Targets' tractability assessment is met for any kind of drug.
Gene: Protein-coding gene on chromosome 2 (38,814 to 46,870, reverse strand). Ensembl gene ENSG00000184731.
Subcellular location: Cytoplasm, cytoskeleton; Cytoplasm, cytoskeleton, microtubule organizing center, centrosome; Cytoplasm, cytoskeleton, spindle pole; Nucleus
Gene Ontology:
Molecular function: alpha-tubulin binding; protein binding
Biological process: positive regulation of cell migration; positive regulation of phosphatidylinositol 3-kinase/protein kinase B signal transduction; regulation of cell projection assembly
Cellular component: cell cortex; nucleus; centrosome; cytoskeleton; spindle pole
Genetic constraint (gnomAD): Loss-of-function variants: 20 observed, 12.6 expected, observed/expected ratio (o/e) 1.59, 90% interval 1.09 to 1.94. The synonymous counts are far from expectation, so gnomAD's model fits this gene poorly and the ratio says little. Missense variants: 547 observed, 373.39 expected, observed/expected ratio (o/e) 1.46, 90% interval 1.37 to 1.57. Synonymous variants: 275 observed, 174.75 expected, observed/expected ratio (o/e) 1.57, 90% interval 1.42 to 1.74.
Homologues: Orthologues: chimpanzee FAM110C (98% identical), macaque FAM110C (94% identical), pig FAM110C (69% identical), rabbit FAM110C (67% identical), dog FAM110C (66% identical), mouse Fam110c (63% identical), rat Fam110c (61% identical), tropical clawed frog fam110c (42% identical), zebrafish fam110c (33% identical). Paralogues in human: FAM110A (27% identical), FAM110B (25% identical), FAM110D (24% identical).
Diseases named in the same sentence as FAM110C in open-access papers:
FAM110C is named in the same sentence as 9 diseases in open-access papers, as found by Europe PMC text mining. Sharing a sentence is not in itself a finding about the gene and the disease. The quoted sentences say what the papers report.
liver cancer (1 paper, 2021). An epithelial or non-epithelial malignant neoplasm that arises from the liver. "For instance, FAM110C and TAT were downregulated after HBx overexpression in human liver cancer cell lines and consistent with our RNA-Seq data, but there was no significant change found in primary mouse hepatocytes following HBx overexpression." (PMID 35036167, 2021).
pancreatic cancer (1 paper, 2024). "It is important to understand the epigenetic regulation and mechanism of FAM110C in pancreatic cancer to develop novel treatment strategies." (PMID 39081276, 2024). "Epigenetic silencing of FAM110C sensitized pancreatic cancer cells to ATR/CHK1 inhibitors." (PMID 39081276, 2024).
cancer (2 papers, 2021 to 2024). A tumor composed of atypical neoplastic, often pleomorphic cells that invade other tissues. "Family with sequence similarity 110C (FAM110C) is a cell fate-related gene and its function in cancer remains unclear." (PMID 39081276, 2024).
infection (1 paper, 2024). The state of being infected such as from the introduction of a foreign agent such as serum, vaccine, antigenic substance or organism. "It is worth noting that some specific proteins involved in microtubule organization are very highly upregulated during infection such as FAM110C and Beta‐Parvin." (PMID 39466906, 2024).
tumor (1 paper, 2024). "In conclusion, FAM110C acts as a potential tumor suppressor in PDAC." (PMID 39081276, 2024). "FAM110C suppressed PDAC cell xenograft growth in mice, implying its potential as a novel tumor suppressor in PDAC." (PMID 39081276, 2024). "FAM110C inhibits PDAC cells growth both in vitro and in vivo, serving as a novel tumor suppressor." (PMID 39081276, 2024). "The tumor weight was 116.68 ± 7.24 vs. 28.98 ± 4.97 mg in MIAPaCa-2 cell xenografts without and with forced expression of FAM110C." (PMID 39081276, 2024).
FAM110C also shares sentences with these, for which no sentence is quoted: hepatocellular carcinoma (1 paper); non-small cell lung carcinoma (1); prostate carcinoma (1); psoriasis (1).